WNT5A (Wnt family member 5A)
Diseases named in the same sentence as WNT5A in open-access papers (continued):
Sharing a sentence is not in itself a finding about the gene and the disease.
lung adenocarcinoma (4 papers, 2016 to 2025). A carcinoma that arises from the lung and is characterized by the presence of malignant glandular epithelial cells. "Our findings reveal a novel function of Rif in mediating Wnt5a-Ror1-Dvl2 signaling, which is associated with the formation of polarized filopodia on 3D matrices in lung adenocarcinoma cells." (PMID 37703992, 2023). "Here, we uncovered a novel function of Rif in mediating Wnt5a-Ror1-Dvl2 signaling, which is associated with the formation of polarized filopodia on 3D matrices in lung adenocarcinoma (LUAD) cells." (PMID 37703992, 2023). "During the pulmonary aging process Wnt4 and Wnt5a were identified as inhibitors of lipid uptake and therefore surfactant production, while Wnt7a triggered differentiation and reduced proliferation of lung adenocarcinoma cell lines, respectively." (PMID 31492143, 2019). "In the present study, the role of the Wnt5a-mediated noncanonical signaling in regulation of characteristics, stemness, and cisplatin-resistance in lung adenocarcinoma A549 and cisplatin-resistant A549 cells was examined in vitro." (PMID 27895670, 2016). "Results showed that the noncanonical Wnt signaling ligand, Wnt5a, could promote the proliferation, migration, invasion, and colony formation in A549 lung adenocarcinoma cells and cisplatin-resistant A549/DDP cells and increase the fraction of ALDH-positive cell in A549/DDP cells." (PMID 27895670, 2016).
lung injury (4 papers, 2015 to 2026). "Furthermore, we demonstrate that Wnt5a isoforms are dysregulated in bleomycin-induced fibrosis and Pseudomonas aeruginosa (PA)-induced acute lung injury and exhibit distinct impacts in Wnt5a isoform expression in response to lung injury." (PMID 42121944, 2026). "WNT-5A has been shown to bind to FZD2 inducing intracellular calcium release and PKC activation in Xenopus and zebrafish embryos and WNT-5A-FZD2-induced calcium spikes in neurons are implicated in traumatic brain injury." (PMID 26514730, 2016).
metastatic carcinoma (4 papers, 2015 to 2024). A carcinoma which has spread from the original site of growth to another anatomic site. "Given the limited effective therapies available for metastatic cancer sufferers, particularly those whose disease has metastasised to the bone, WNT5A presents as a potential putative target for therapy." (PMID 39164966, 2024).
oral squamous cell carcinoma (4 papers, 2016 to 2025). "WNT5a has been implicated in the development and progression of several tumor types, including oral cavity tumors, with high WNT5a expression reported in oral squamous cell carcinoma and ameloblastoma." (PMID 40457691, 2025). "Wnt5a can regulate cellular signaling through non-canonical Wnt signaling pathways, with reported roles in the development and progression of various tumor types 15, including elevated Wnt5a expression in oral squamous cell carcinoma, tongue cancer and ameloblastoma 16-18." (PMID 32742496, 2020).
papillary thyroid cancer (4 papers, 2022 to 2025). "FAM230B is upregulated in papillary thyroid cancer and increases the expression levels of WNT5A by sponging miR-378a-3p to accelerate tumor metastasis." (PMID 36262247, 2022). "FAM230B is also highly expressed in papillary thyroid cancer and interacts with the miR-378a-3p/WNT5A axis to accelerate tumor metastasis." (PMID 35287554, 2022).
periodontal disease (4 papers, 2014 to 2022). "Studies investigating the GCF levels of Sclerostin and WNT-5a after periodontal therapy may further elucidate the role of these molecules in the pathogenesis of periodontal disease and evaluate their potential diagnostic and prognostic values." (PMID 34440994, 2021). "The roles of Wnt5a in osteoclastogenesis are potentially related to tooth eruption and alveolar bone remodeling in periodontal diseases, although little experimental evidence currently exists in support of these putative roles." (PMID 25510849, 2014). "H. pylori infection has been associated with higher levels of key periodontal pathogens and was found to enhance the expression of IL-8 and Wnt5a, suggesting it may act as an aggravating factor for periodontal disease." (PMID 35132337, 2022). "Wnt5a appears to play important roles in the fate of DFSCs in development, homeostasis and perhaps regeneration of the periodontium, with potential implications in tooth eruption, orthodontic tooth movement, dental implant bone healing and periodontal disease." (PMID 25510849, 2014).
pulmonary hypertension (4 papers, 2011 to 2021). Increased pressure within the pulmonary circulation due to lung or heart disorder. "Thus, dysregulated Wnt signaling in the RV, secondary to pulmonary hypertension, may underlie development of RV dysfunction, and this may partly reflect an imbalance between Wnt5a and its antagonist sFRP3." (PMID 28615692, 2017). "Patients with PASP > 40 mm Hg (median 51), indicating pulmonary hypertension, had a markedly higher Wnt5a/sFRP3 ratio." (PMID 28615692, 2017). "Our present study demonstrated that administration of MSC‐EXO could significantly reduce pulmonary hypertension (PH) vascular remodelling, through regulation of Wnt5a/BMP signalling pathway." (PMID 33090702, 2020). "Expression of Wnt ligands (Wnt1, Wnt3a, and Wnt5a) and Wnt signaling upstream regulator genes (Frizzled1 and 2 receptors and sFRP-1) and intracellular effectors (Axin1 and GSK3β) were investigated in pulmonary hypertensive rat lungs, 3 and 5 weeks after MCT injury." (PMID 21533110, 2011). "On the other hand, induction of Wnt5a overexpression in recombinant mice significantly inhibits β-catenin expression, human PASMC proliferation, and subsequent hypoxia-induced pulmonary hypertension." (PMID 34434114, 2021). "β-Catenin is a transcription factor involved in PASMC proliferation, and its expression can be inhibited by Wnt5a (in a non-canonical Wnt pathway) in hypoxia-induced pulmonary hypertension." (PMID 34434114, 2021).
triple-negative breast carcinoma (4 papers, 2016 to 2025). An invasive breast carcinoma which is negative for expression of estrogen receptor (ER), progesterone receptor (PR), and human epidermal growth factor receptor 2 (HER2). "Lower levels of Wnt-5A expression are significantly associated with poor prognosis and more aggressive behavior in triple-negative breast cancer." (PMID 40226410, 2023). "Additionally, in triple-negative breast cancer, Wnt5a was reduced after selamectin treatment." (PMID 40569965, 2025).
tuberculosis (4 papers, 2014 to 2022). A chronic, recurrent infection caused by the bacterium Mycobacterium tuberculosis. "Macrophage-associated WNT5A expression was initially described in tuberculosis lung granulomas, and WNT5A and FZD4 mRNA expression was significantly elevated in peripheral blood mononuclear cells of tuberculosis patients." (PMID 31781093, 2019). "With regard to TB, however, it remains elusive whether excessive Wnt5a formation may contribute to the M. tuberculosis-induced immunopathology." (PMID 28082976, 2016).
urothelial carcinoma (4 papers, 2013 to 2024). A malignant neoplasm derived from the transitional epithelium of the urinary tract (urinary bladder, ureter, urethra, or renal pelvis). "We utilized a large dataset of urothelial carcinoma (UC) tumors to characterize non‐canonical WNT signaling through WNT5A, ROR1, ROR2, or FZD2 expression." (PMID 38558536, 2024). "Our group recently reported a positive correlation between the expression of Wnt5a, a member of the Wnt proteins family, and histopathological grade and stage of urothelial carcinoma (UC)." (PMID 28427201, 2017). "The role of the WNT5A pathway (WNT5A, ROR1, ROR2, and FZD2) in the pathogenesis and progression of urothelial carcinoma (UC) has not been fully elucidated." (PMID 38558536, 2024). "Wnt5a mRNA expression was compared among three cells lines: a normal urothelial cell line (NUC) and two different urothelial carcinoma cell lines (J82 and T24)." (PMID 23947922, 2013).
allergic asthma (3 papers, 2013 to 2023). A asthma with a basis in a pathological type I hypersensitivity reaction. "What is known about Wnt5A in allergic asthma, IPF and COPD, and its role in the pathogenesis of these diseases?" (PMID 36658268, 2023). "As we were specifically interested in the effects of induced WNT5A in the context of allergic asthma, we subjected both WT and Tg mice to chronic ovalbumin exposure to induce an allergic state." (PMID 32317758, 2020). "As such, the regulation of IL31 may in part explain the Th2 skewing we observed in the WNT5A transgenic mouse and support a potential role for WNT5A in Th2 type inflammation and allergic asthma." (PMID 32317758, 2020).
astrocytoma (3 papers, 2010 to 2020). "Several of these genes, including MYC, EGFR, HIF1A, HGF, APOE, TIMP3, and WNT5A have been identified as being important to development of astrocytoma." (PMID 23737970, 2013). "Many of the genes have in fact been implicated in development of astrocytoma, including EGFR, HIF-1α, c-Myc, WNT5A, and IDH3A." (PMID 23737970, 2013). "In astrocytoma, the level of Wnt-2, Wnt-5a and β-catenin protein is strikingly increased compared with normal brain tissue." (PMID 20334650, 2010). "Consistently, higher expression of WNT5A in GBM, Anaplastic Astrocytoma and anaplastic oligodendroglioma was observed; while lower expression of WNT 10B in GBM, oligodendroglioma, astrocytoma and anaplastic astrocytoma was detected." (PMID 32181818, 2020).
atrial fibrillation (3 papers, 2023 to 2025). A disorder characterized by an electrocardiographic finding of a supraventricular arrhythmia characterized by the replacement of consistent P waves by rapid oscillations or fibrillatory waves that vary in size, shape and timing and are accompanied by an irregular ventricular response. "Candesartan reduced the atrial fibrosis in a rat model through the suppression of connective tissue growth factor, while Losartan inhibited frizzled 8 and downregulated the WNT-5A pathway in an atrial fibrillation fibrosis reduction model in rats." (PMID 37509613, 2023). "In a research including patients with rheumatic valve disease undergoing valve surgery, atrial fibrillation was associated with increased expression of the transcription factor SNAIL1 and other WNT ligands, including the non-canonical WNT ligands WNT5A and WNT11, in the right atrium." (PMID 39482911, 2025). "In research including patients with rheumatic valve disease undergoing valve surgery, atrial fibrillation was associated with increased expression of the transcription factor SNAIL1 and other WNT ligands, including the non-canonical WNT ligands WNT5A and WNT11, in the right atrium." (PMID 39482911, 2025).
autosomal dominant Robinow syndrome (3 papers, 2024 to 2025). "Previously, our laboratory has investigated the effects of autosomal dominant Robinow syndrome WNT5A variants on jaw and limb development, and the effects of DVL1 variants on limb development." (PMID 38967226, 2024). "All variants known to cause autosomal dominant Robinow syndrome occur in genes within the Wnt signaling pathway (DVL1, DVL3, or WNT5A)." (PMID 40796658, 2025). "WNT5A-driven Wnt/Planar Cell Polarity (Wnt/PCP) signaling is essential for vertebrate limb morphogenesis, and pathogenic WNT5A variants cause autosomal dominant Robinow Syndrome (RS)." (PMID 41510274, 2025). "Previous studies from our laboratory have demonstrated that autosomal dominant Robinow syndrome WNT5A and DVL1 variants have dominant-negative effects on chondrogenesis, leading to abnormal bone morphology." (PMID 38967226, 2024). "Indeed, our previous work on autosomal dominant Robinow syndrome DVL1 frameshift mutations (1519ΔT, 1529ΔG and 1615ΔA) and a WNT5A missense mutation (248G>C) found that the variants retained activity and were sufficient to reduce size and change bone shape." (PMID 38967226, 2024). "Of these, receptor tyrosine kinase-like orphan receptor 2 (ROR2) and nucleoredoxin (NXN) are linked to autosomal recessive Robinow syndrome, whereas dishevelled genes (DVL1, DVL2 and DVL3), WNT5A and Frizzled2 (FZD2) have autosomal dominant inheritance (autosomal dominant Robinow syndrome)." (PMID 38967226, 2024).
cardiac hypertrophy (3 papers, 2021 to 2025). "Wnt5a, another component of Wnt signaling pathway, also induces cardiac hypertrophy by activating the Wnt/PCP pathway." (PMID 35717150, 2022). "It has been reported that Wnt5a is derived from fibroblasts or myofibroblasts and induces cardiac hypertrophy by Dapper-1." (PMID 34564708, 2021). "This discovery implies that wnt5A may indirectly control ventricular hypertrophy through neutrophils and the heart’s local inflammatory response." (PMID 39482911, 2025). "Interestingly, myeloid-specific Wnt5a knockdown and neutrophil depletion both decreased cardiac hypertrophy and neutrophil infiltration in a mouse model of left ventricular hypertrophy brought on by aortic constriction." (PMID 39482911, 2025).
chronic lung disease (3 papers, 2019 to 2025). According to the definitions of the American and British Thoracic Societies, including pulmonary functional tests, X-rays, and CT scans for items such as fibrosis, bronchiectasis, bullae, emphysema, nodular or lymphomatous abnormalities. "Studies confirm that hyperoxia abnormally activates the Wnt/β‐catenin pathway through the NF‐κB‐Wnt5a signaling axis, leading to alveolarization impairment and fibrosis, suggesting Wnt5a as a potential therapeutic target for chronic lung diseases including BPD." (PMID 40865553, 2025). "Aberrant expression of the non-canonical ligands WNT-5A and WNT-5B has been reported to contribute to inflammation, stem cell ageing, and chronic lung diseases; however, their impact on alveolar epithelial repair is unclear." (PMID 31557955, 2019).
differentiated thyroid carcinoma (3 papers, 2013 to 2025). Differentiated thyroid carcinoma (DTC), also known as papillary or follicular thyroid carcinoma, is a slow-growing malignancy usually presenting in adults as an asymptomatic thyroid mass. "Wnt5a is expressed in follicular adenoma (FA), papillary thyroid carcinoma (PTC), and follicular thyroid carcinoma (FTC); no expression has been detected in anaplastic thyroid carcinomas (ATC) or in the normal thyroid." (PMID 26608372, 2016).
dilated cardiomyopathy (3 papers, 2017 to 2022). Cardiomyopathy which is characterized by dilation and contractile dysfunction of the left and right ventricles. "Elevated basal WNT-5a plasma concentrations have been described in patients with dilated cardiomyopathy and were associated with right ventricular dysfunction, especially in patients with more advanced disease." (PMID 36440011, 2022). "In the failing myocardium, Wnt5a was most prominently upregulated in cardiac fibroblasts and elevated circulating Wnt5a levels were associated with adverse outcomes in patients with dilated cardiomyopathies." (PMID 29564334, 2018).
Ewing sarcoma (3 papers, 2014 to 2025). A small round cell tumor that lacks morphologic, immunohistochemical, and electron microscopic evidence of neuroectodermal differentiation. "To confirm that there was no significant activation of the canonical, beta-catenin-dependent signaling pathway by recombinant Wnt5a in Ewing sarcoma cell lines, we performed a TOPFlash assay for beta-catenin-dependent transcriptional activity." (PMID 41301074, 2025). "Our data demonstrate a significant role of Wnt5a in the formation of focal adhesions in Ewing sarcoma." (PMID 41301074, 2025). "Ewing sarcoma xenografts in mice treated with WNT974 also demonstrated a statistically significant increase in endogenous Wnt5a transcription." (PMID 41301074, 2025). "Wnt5a knock-out Ewing sarcoma cell lines were generated using Crispr-Cas9 editing to evaluate changes in migration and cytoskeletal arrangements." (PMID 41301074, 2025). "Ewing sarcoma cells modulate their endogenous transcription of Wnt5a upon differing concentrations of exogenous Wnt5a exposure, suggesting an important feedback-dependent response." (PMID 41301074, 2025). "This assay demonstrates that there is less palmitoylated Wnt5a present in the Ewing sarcoma cells treated with WNT974, reflected by the fainter band in WNT974-treated samples compared to control." (PMID 41301074, 2025). "Taken together, our findings with Wnt5a knock-out cells confirm the implications of our previous data, that Wnt5a is a key mediator of Ewing sarcoma migration through modulation of cytoskeletal structure and interactions with cell membrane-associated adhesion molecules." (PMID 41301074, 2025). "To prove this point, we generated Wnt5a knock-out Ewing sarcoma cell lines." (PMID 41301074, 2025). "In fact, deleting Wnt5a from Ewing sarcoma cells by CRISPR-mediated gene editing phenocopies treatment with the pan-Wnt inhibitor, WNT974, providing direct mechanistic evidence that Wnt5a is a key driver of a pathway that is critical for Ewing sarcoma metastasis." (PMID 41301074, 2025). "In addition, the increased Wnt5a transcription correlates with markedly increased expression of Wnt5a protein in the Ewing sarcoma xenografts, demonstrating that tumors in vivo respond to WNT974 similarly to cell lines in vitro." (PMID 41301074, 2025). "Therefore, any transcriptional, translational, or migratory changes seen in the Ewing sarcoma cells treated with exogenous recombinant Wnt5a result from activation of a beta-catenin-independent Wnt signaling pathway." (PMID 41301074, 2025). "Ewing sarcoma cell lines deprived of autocrine/paracrine Wnt signals by treatment with WNT974 dramatically and specifically upregulate Wnt5a." (PMID 41301074, 2025). "Taken together, our results support the model that Wnt5a-dependent signaling drives phosphorylation of FAK and Src, and that both FAK and Src activation are necessary for Wnt5a-dependent Ewing sarcoma cell migration." (PMID 41301074, 2025). "In this study, we show that a non-canonical Wnt signaling pathway drives Ewing sarcoma migration, with Wnt5a being a key regulator of this mechanism." (PMID 41301074, 2025). "Supporting the concept that this non-canonical Wnt signaling pathway is important for Ewing sarcoma biology is the observation that Wnt5a is a direct transcriptional target of EWS-FLI1." (PMID 41301074, 2025). "Our data suggests that Wnt5a is a major regulator of Ewing sarcoma cell migration, and that inhibition of a Wnt5a-dependent autocrine/paracrine signaling pathway is the mechanism by which WNT974 suppresses Ewing sarcoma metastasis." (PMID 41301074, 2025). "Our work clearly demonstrates that there is a feedback loop operative with non-canonical, Wnt5a-dependent signaling as well in Ewing sarcoma." (PMID 41301074, 2025). "Recombinant Wnt5a does not activate beta-catenin-dependent signaling to a significant degree in Ewing sarcoma cells." (PMID 41301074, 2025).